ICAM1 (intercellular adhesion molecule 1)
Diseases named in the same sentence as ICAM1 in open-access papers (continued):
Sharing a sentence is not in itself a finding about the gene and the disease.
endothelial dysfunction (continued). "It is not clear if the rise of AM and the decline of b- FGF levels may be consequences or predisposing factors for VCAM-1 and ICAM-1 elevation as these endothelial dysfunction biomarkers could reduce peripheral blood flow and vascular integrity." (PMID 25287126, 2014). "Consistent with the hypothesis that Hcy mechanistically relates to SVD through endothelial dysfunction, the authors found that including other markers of endothelial dysfunction, ICAM-1 and TM, in a logistic regression model resulted in the loss of the significant association between Hcy and SVD." (PMID 37685924, 2023). "However, only treatment with BBR reduces TNFα-induced expression of vascular cell adhesion molecule-1 (VCAM-1) and intercellular adhesion molecule-1 (ICAM-1) associated with endothelial dysfunction, possibly through phosphorylation of MAPK/ERK1/2, compared to treatment with lovastatin." (PMID 38034996, 2023). "In addition, endothelial cell activation, mechanistically closely linked to endothelial dysfunction, is characterized by an upregulated expression of intracellular, vascular, and leukocyte adhesion molecules on the surface of endothelial cells (ICAM-1, ICAM-3, VCAM-1, E-selectin)." (PMID 35883760, 2022). "Sterile inflammation, caused by endothelial injury, leads to endothelial dysfunction via cytokines (IL-6, TNF-α, CRP) and the activation of NF-κB, increasing adhesion molecule (VCAM-1, ICAM-1, E-selectin) expression." (PMID 40299499, 2025). "VEGF functions with intercellular adhesion molecule-1 (ICAM-1) to promote leukocyte adhesion, endothelial dysfunction, and BRB breakdown." (PMID 40807437, 2025). "Resistin is associated with various biological processes, including the proliferation of endothelial cells, angiogenesis, the expression of VCAM-1 and ICAM-1 in endothelial cells, and the generation of ROS, which contribute to endothelial dysfunction." (PMID 40943241, 2025). "In primary feto-placental endothelial cells from GDM pregnancies, there was a decrease in ICAM-1, a marker of endothelial dysfunction." (PMID 40453589, 2025). "EMP, ADMA, VCAM-1 (Vascular Cell Adhesion Molecule-1), and ICAM-1 (Intercellular Adhesion Molecule-1) reflect endothelial dysfunction and vascular inflammation." (PMID 40949500, 2025). "QPCR assays showed that the mRNA levels of inflammatory cytokines (IL-1β) and adhesion molecules (ICAM-1 and MCP-1) associated with endothelial dysfunction were elevated to varying degrees in OGD/OGR treated cells while SCU reversed these phenomena." (PMID 40098620, 2025). "Elevated endocan levels have been proposed not only as a biomarker but also as a mediator of endothelial dysfunction, via its regulation of ICAM-1/VCAM-1 expression and oxidative stress pathways." (PMID 40863140, 2025). "Women with previous GDM displayed lower flow-mediated dilation, higher values of markers of endothelial dysfunction, such as E-selectin and intercellular adhesion molecule-1 (ICAM-1), and decreased levels of L-arginine (a critical substrate for NO synthesis)." (PMID 40453589, 2025). "Surgery can induce endothelial dysfunction, leading to increased expression of adhesion molecules like ICAM-1 (Intercellular Adhesion Molecule-1) and VCAM-1 (Vascular Cell Adhesion Molecule-1) on endothelial cells." (PMID 40806279, 2025). "ICAM-1 was viewed as a symbol of endothelial dysfunction leading to vascular disorders, and its level was increased in GDM maternal serum and the umbilical–placental circulation." (PMID 40453589, 2025). "This indicates that the induction of ICAM-1 and endothelial dysfunction cannot be ascribed to a direct effect of IL-6 but it is rather a long-lasting change." (PMID 40599782, 2025).
endothelial dysfunction (continued). "Markers of endothelial dysfunction, such as circulating E‐selectin and intercellular adhesion molecule 1 (ICAM‐1) were found to be elevated in women with a history of GDM 6.5 years after delivery." (PMID 41017344, 2025). "After alcohol cessation Lyve1 and Stab2 expression returned to control levels, but in contrast, Icam1, Vcam1, and Cd34 stayed elevated or further increased suggesting that endothelial dysfunction persists after alcohol cessation." (PMID 40288442, 2025). "Based on this, we further performed immunofluorescence and found that the expression of ICAM-1 increased and ZO-1 decreased after IL-6 intervention, indicating endothelial dysfunction at this time." (PMID 38195507, 2024). "ET-1, E-selectin, ICAM-1, and VCAM-1, expressed in various disease states associated with endothelial dysfunction, serve as reliable markers of inflammation and endothelial dysfunction, playing crucial roles in the pathophysiology of cardiovascular diseases." (PMID 38251031, 2024). "Markers of inflammation (CRP, LDH, IL6), endothelial dysfunction (ICAM1, VCAM1, E-selectin), coagulation (fibrinogen) and fibrinolysis (D dimers) are used in assessing disease severity, prognosis and treatment options." (PMID 38474287, 2024). "Studies have shown that individuals with CD exhibit signs of endothelial dysfunction, including impaired flow-mediated dilation and elevated levels of endothelial activation markers such as von Willebrand factor and soluble intercellular adhesion molecule-1." (PMID 39150613, 2024). "ICAM-1 and VCAM-1 contribute to vascular inflammation, and these markers have been widely utilized as indicators of endothelial dysfunction, demonstrating a significant association with cardiovascular disease (CVD) risk and mortality in the general population." (PMID 39669584, 2024). "Specifically, this cluster of correlation has high levels of serum occludin, IL-6 receptor (IL-6R), soluble intercellular adhesion molecule-1 (sICAM-1) and vascular endothelial (VE)-cadherin, with potential inflammatory-induced endothelial dysfunction." (PMID 39182041, 2024). "ICAM-1 recruitment of excessive white blood cells can exacerbate the inflammatory process and, in many cases, exacerbate tissue damage High expression of ICAM-1 can lead to endothelial dysfunction and inflammatory processes." (PMID 38195507, 2024). "The oxidative stress damages vascular endothelial cells, leading to endothelial dysfunction and increased expression of chemokines and adhesion molecules, including ICAM-1 and VCAM-1." (PMID 39452916, 2024). "Endothelial dysfunction is characterized by the overexpression of adhesion molecules, including intercellular adhesion molecule-1 (ICAM-1) and vascular cell adhesion molecule-1 (VCAM-1)." (PMID 39457107, 2024). "Expression of ICAM-1 as a marker of endothelial dysfunction was lower in the DN group compared to the HTK group (p = 0.02)." (PMID 39741661, 2024). "One of the phenotypic features of endothelial dysfunction is the upregulation of cellular adhesion molecules (ICAM-1 and VCAM-1) and an increase in the expression of intercellular monocyte adherence to the endothelium." (PMID 39409189, 2024). "VCAM1 and ICAM1 are potential targets of biochanin A that are involved in AGE-RAGE signaling pathways and are associated with endothelial dysfunction." (PMID 38195507, 2024). "The findings regarding increased ICAM-1 expression in endothelial cells in vitro further underscore the direct impact of pathogens like CHIKV on endothelial dysfunction." (PMID 39513877, 2024). "Resveratrol has been found to enhance total antioxidant ability and reduce levels of endothelial dysfunction biomarkers, such as vWF, ICAM‐1, and caspase 3 in endothelial cells and umbilical arteries from patients with preeclampsia." (PMID 39040847, 2024).
endothelial dysfunction (continued). "Their concentrations, particularly VCAM-1, ICAM-1, and ESAM, have been shown to be associated with endothelial dysfunction, vascular damage, and increased risk of atherosclerotic cardiovascular disease." (PMID 39234240, 2024). "The overexpression of cell adhesion molecules (CAMs), including VCAM-1, ICAM-1, and E-selectin, in vascular endothelial cells is a phenotypic characteristic of endothelial dysfunction." (PMID 39065776, 2024). "We observed a lower percentage of endothelial cells with ICAM-1 expression in the DN group, which contributes to inflammation, leukocyte adhesion, and vascular permeability ultimately triggering endothelial dysfunction." (PMID 39741661, 2024). "In the context of endothelial dysfunction and leukocyte transmigration into the intimal layer, ICAM-1 and E-selectin were consistently expressed at significant levels." (PMID 38306519, 2024). "Endothelial dysfunction is characterized by increased expression of cellular adhesion molecules such as ICAM-1 and VCAM-1." (PMID 39408198, 2024). "It was found that biochanin A can promote the expression of ZO-1, reduce the expression of ICAM-1, which means improving endothelial dysfunction." (PMID 38195507, 2024). "This increases monocyte adhesion through an increase in intercellular adhesion molecule 1 (ICAM1) and E-selectin, enhancing endothelial dysfunction." (PMID 39337693, 2024). "We demonstrated in vitro that the expression of ICAM-1 was increased and the expression of ZO-1 was decreased after IL-6 induced endothelial dysfunction." (PMID 38195507, 2024). "In human atherosclerotic lesions, endothelial cells have been shown to over-express intracellular VCAM-1, ICAM-1, and E-selectin in order to promote leukocyte adhesion and eventually stimulate endothelial dysfunction." (PMID 37112618, 2023). "To determine the potential role of hispidulin in endothelial dysfunction, we examined its effect on P. gingivalis LPS-induced ICAM-1." (PMID 37764491, 2023). "The last group showed greater changes in biomarkers that induce endothelial dysfunction and inflammation, with an increase in the levels of inflammatory molecules and cytokines, which are expressed with a slight increase in ICAM-1 and TNF-a." (PMID 38162982, 2023). "Markers of endothelial dysfunction [plasma E-selectin, intracellular adhesion molecule 1 (ICAM-1) and VCAM-1] increased 2 h or/and 4 h after a high-AGEs meal compared with 2 h or/and 4 h after a low-AGEs meal." (PMID 37111220, 2023). "NF‐κB activation is a critical regulator of CAMs including ICAM‐1 and VCAM‐1 which causes the adhesion of monocytes to endothelial cells during endothelial dysfunction." (PMID 37457144, 2023). "We showed endothelial dysfunction in cultured CiGEnCs evidenced by enhanced transcription and translaton of ICAM-1, VCAM-1, vWF, and ET-1 in response to Ang II stimulation to simulate the activated renin-angiotensin system in patients with malignant HTN." (PMID 37188751, 2023). "ICAM-1 is a surface cellular glycoprotein potentially involved in the processes of inflammation, also serving as a biomarker of endothelial dysfunction." (PMID 37368372, 2023). "Endothelial dysfunction suppresses eNOS activity and NO production while inducing the expression of adhesion molecules, such as ICAM-1, VCAM-1, and P-selectin, to promote the adhesion of monocytes and platelets to the endothelium." (PMID 38139268, 2023). "Taken together, these studies support the view that high serum ICAM-1 and VCAM-1, as biomarkers of endothelial dysfunction and vascular damage, are associated with ventricular de/repolarization." (PMID 36710676, 2023). "Hypercoagulability, endothelial dysfunction (increased ICAM-1 levels), and inflammation (increased IL-6 levels) can still be detected in some patients approximately 1 year after recovery from COVID-19." (PMID 37896963, 2023). "ICAM-1, as a biomarker of endothelial dysfunction, is increased in sera and detected in spontaneous wheals of patients with CIU." (PMID 38045687, 2023).
endothelial dysfunction (continued). "Endothelial dysfunction is an early indicator of AS, characterized by overexpression of adhesion molecules, including intercellular adhesion molecule-1 (ICAM-1) and vascular cell adhesion molecule-1 (VCAM-1)." (PMID 37325477, 2023). "Endothelial dysfunction is characterized by the activation of endothelial cells and consequent upregulation of adhesion molecules on their surface, including ICAM-1 and VCAM-1." (PMID 37432255, 2023). "Our results reveal successively increasing levels of sIS from the C to P3 subgroups, a positive correlation of indoxyl sulfate with markers of endothelial dysfunction (ICAM-1) and PI R-ACI, and a good differentiation between the P1 vs. C and P2 subgroups." (PMID 37623837, 2023). "Several biomarkers have been associated with endothelial dysfunction in PAD, including adhesion molecules (intercellular adhesion molecule 1 [ICAM-1] and vascular cell adhesion protein 1 [VCAM-1]) and selectins (E-selectins and P-selectins)." (PMID 37446302, 2023). "Endothelial dysfunction, an early phase of vascular inflammation in humans, commences with ICAM-1 and VCAM-1 expression and immune cell adhesion." (PMID 37382544, 2023). "The proinflammatory vascular adhesion molecules VCAM-1 and ICAM-1 are biomarkers of endothelial dysfunction." (PMID 36432506, 2022). "Endothelial dysfunction in KD by endothelial biomarkers (E-selectin, P-selectin,intercellular adhesion molecule-1 (ICAM-1), and vascular cellular adhesionmolecule-1 (VCAM-1)) was identified as early in 1992." (PMID 39076622, 2022). "Markers of endothelial dysfunction (ICAM1, VCAM, VEGFR3, thrombomodulin) and inflammatory response (CRP, MPO) were also noted to progressively increase with rising altitude in both groups, more prominently so in ICs and has been reported earlier by us." (PMID 37384264, 2022). "Nevertheless, we showed that RSV incubation downregulates endothelial dysfunction genes such as ICAM-1, vWF, and CASP-3 in endothelial cells and umbilical arteries of patients with PE." (PMID 36358483, 2022). "Another repercussion of the endothelial dysfunction in PE is the increase of endothelial activation biomarkers such as intercellular adhesion molecule-1 (ICAM-1), von Willebrand factor (vWF), and Caspase-3 (CASP-3)." (PMID 36358483, 2022). "The study also demonstrated homoarginine levels were inversely related to markers of endothelial dysfunction (e.g., ICAM-1 and VCAM-1)." (PMID 35722087, 2022). "HUVECs incubated with sera of PE patients showed increased expression of endothelial dysfunction marker mRNAs, such as intercellular adhesion molecule-1 (ICAM-1), von Willebrand factor (vWF), and Caspase-3 (CAS-3)." (PMID 36558404, 2022). "TNF-α is reported to trigger the interaction between monocytes and vascular endothelial cells, enhance the expression of adhesion molecules, such as VCAM-1, ICAM-1, and E-selectin, and finally induce endothelial dysfunction." (PMID 36278191, 2022). "The protein expressions of endothelial dysfunction markers including ICAM-1 and VCAM-1 were upregulated in shFGA and HG groups, while CD31 and vWF were significantly downregulated." (PMID 35399949, 2022). "Sepsis predictably increased serum concentration of acute, proinflammatory cytokines, such as IL-6, as well as markers of endothelial dysfunction markers (ICAM-1 and angiopoietin 2)." (PMID 35286340, 2022). "For the five endothelial dysfunction biomarkers, higher EDIH scores were associated with greater concentration of E-selectin (2.8%) and ICAM-1 (5.%)." (PMID 34616762, 2021). "The upregulation of vascular cell adhesion protein 1, intercellular adhesion molecule 1, monocyte chemoattractant protein 1, and IL-6 leads to endothelial dysfunction, monocyte recruitment, and inflammatory response." (PMID 34596673, 2021).
endothelial dysfunction (continued). "The obtained results show that hepatitis C group had significantly higher concentrations of ICAM-1 and sVCAM-1 compared to controls which is in accordance with most results of previous studies dealing with HCV, endothelial dysfunction and higher risk of CVD." (PMID 33520470, 2021). "In the derivation cohort, the Hypolipoprotein phenotype had significantly lower total cholesterol, HDL-C, LDL-C, PON-1, ApoA-I, and higher ICAM-1, indicative of more severe endothelial dysfunction." (PMID 34535154, 2021). "eNOS downregulation and MCP-1, VCAM-1 and ICAM-1 upregulation with subsequent macrophage accumulation provided compelling evidences on HFHF induced endothelial dysfunction and activation that were also observed in OxLDL treated- and HSP60 overexpressing-HUVEC." (PMID 33441791, 2021). "Along with soluble adhesion molecules such as E-selectin and vascular cell adhesion molecule 1 (VCAM-1), ICAM-1 represent a molecular marker of endothelial dysfunction." (PMID 33924229, 2021). "ICAM-1 is considered an initiator of inflammatory cell adhesion and is also closely related to endothelial dysfunction, playing an important role in the development of cardiovascular disease." (PMID 34589453, 2021). "IL-1β, IL-6, and ICAM-1 are important proinflammatory molecules, which play crucial roles in the preliminary inflammatory response and endothelial dysfunction." (PMID 34221236, 2021). "It was reported that higher levels of ICAM-1 and VCAM-1, two adhesion molecules, were associated with impaired endothelial dysfunction in active AS." (PMID 34259096, 2021). "Circulating levels of ICAM-1, reflecting endothelial dysfunction, were similarly increased in both COVID-19 and septic shock patients, compared to matched controls." (PMID 35111777, 2021). "A Hypolipoprotein sepsis phenotype was identified and characterized by lower lipoprotein levels, increased endothelial dysfunction (ICAM-1) and organ failure, and worse clinical outcomes." (PMID 34535154, 2021). "For the derivation cohort, patients in the Hypolipoprotein cluster were characterized by lower cholesterol levels, increased endothelial dysfunction (ICAM-1), and higher SOFA scores." (PMID 34535154, 2021). "Unsurprisingly, measures of endothelial dysfunction (E-selectin and ICAM-1) and inflammatory markers (IL-8, IL-6, and IP-10) also demonstrated significant differences between rapid recovery, CCI, and early death groups." (PMID 34535154, 2021). "The Hypolipoprotein phenotype was characterized by lower lipoprotein levels, increased endothelial dysfunction (ICAM-1), higher SOFA scores, and worse clinical outcomes (45% rapid recovery, 40% CCI, 16% early death; 28-day mortality, 21%)." (PMID 34535154, 2021). "A previous study reports hyperglycemia-induced human endothelial dysfunction via an increase in intercellular adhesion molecule-1 (ICAM-1), VCAM-1 expression, and reduced Gas6/Axl expression." (PMID 34326776, 2021). "The Kruskal–Wallis analysis of variance revealed an effect of rs2228145 (A > C) genotype on the transcriptional activity of ICAM1, which argues for its role in the pathogenesis of endothelial dysfunction and essential hypertension." (PMID 33659786, 2020). "Cytokine IL-6 is involved in the development of endothelial dysfunction by regulating the expression of the VCAM1 and ICAM1 genes, encoding intercellular adhesion molecules." (PMID 33659786, 2020). "The endothelial dysfunction pathway (represented by soluble intercellular adhesion molecule-1 (sICAM-1) and soluble E-selectin (sE-selectin)) and lipid-related pathway were among the top five pathways for both diseases." (PMID 32164753, 2020). "In conclusion, we demonstrated that ZnONPs induce endothelial dysfunction by increasing inflammatory adhesion molecule ICAM-1 expression and disrupting both tight and adherens junctions." (PMID 32414036, 2020).